OR2B6 (olfactory receptor family 2 subfamily B member 6)
Description:
Odorant receptor.
Synonyms: OR5-40; OR6-31; OR2B1; OR2B1P; OR2B5; OR2B6P; dJ408B20.2; OR5-41
Tractability: Antibody: UniProt places it where antibodies can reach, with medium confidence; UniProt predicts a signal peptide or a membrane-spanning region; its Gene Ontology location is reachable by antibodies, with medium confidence.
Gene: Protein-coding gene on chromosome 6 (27,957,241 to 27,958,182, forward strand). Ensembl gene ENSG00000124657.
Subcellular location: Cell membrane
Pathways (Reactome):
Sensory Perception: Expression and translocation of olfactory receptors
Gene Ontology:
Molecular function: olfactory receptor activity; G protein-coupled receptor activity
Biological process: detection of chemical stimulus involved in sensory perception of smell; G protein-coupled receptor signaling pathway
Cellular component: plasma membrane; membrane
Genetic constraint (gnomAD): Loss-of-function variants: 0 observed, 0.17 expected, observed/expected ratio (o/e) 0, 90% interval 0 to 1.88. That is too few expected variants to judge how well the gene tolerates losing a copy. Missense variants: 344 observed, 381.59 expected, observed/expected ratio (o/e) 0.9, 90% interval 0.82 to 0.99. Synonymous variants: 128 observed, 147.98 expected, observed/expected ratio (o/e) 0.87, 90% interval 0.75 to 1.
Homologues: Orthologues: chimpanzee OR2B6 (97% identical), pig OR2B6 (86% identical), rabbit OR2B6 (84% identical), mouse Or2b6 (81% identical), rat Or2b2 (78% identical). Paralogues in human: OR2B2 (80% identical), OR2B3 (71% identical), OR2G3 (58% identical), OR2J3 (58% identical), OR2W3 (58% identical), OR2B11 (58% identical), OR2J2 (58% identical), OR2J1 (57% identical), OR2G2 (55% identical), OR2H2 (55% identical), OR2C3 (55% identical), OR2C1 (55% identical), and 80 more.
Diseases named in the same sentence as OR2B6 in open-access papers:
OR2B6 is named in the same sentence as 15 diseases in open-access papers, as found by Europe PMC text mining. Sharing a sentence is not in itself a finding about the gene and the disease. The quoted sentences say what the papers report.
breast carcinoma (8 papers, 2018 to 2024). "OR51E2 overexpression has been linked to cancer cell proliferation and migration, while OR2B6 overexpression in breast carcinoma contributes to invasive behavior and metastatic potential." (PMID 39769144, 2024). "Nonetheless, our data is more comprehensive as we confirmed OR2B6 upregulation in a large number of invasive breast carcinoma population and moreover, identified correlations among OR2B6 and breast cancer-related genes associated with cancer cell proliferation." (PMID 31551495, 2019). "Thus, our data indicate that OR2B6 expression is associated with breast carcinoma and therefore might be considered as a potential tumor marker." (PMID 29497600, 2018). "For instance, OR2B6 overexpression has been reported in breast cancer, and OR51E1 has been found to be elevated in advanced prostate cancer and other solid tumors, consistent with our findings." (PMID 39769144, 2024). "Olfactory gene OR2B6 is expressed in over 80% of breast carcinoma tissues and its expression has been suggested as a potential biomarker in breast carcinoma." (PMID 37379307, 2023). "We examined the significance of OR transcript abundance in a large invasive breast carcinoma population and identified two OR genes, OR2W3 and OR2B6 to be potentially correlated to breast cancer progression." (PMID 31551495, 2019). "Another study examined the expression of OR2B6 among 6 human breast carcinoma samples and confirmed OR2B6 protein expression in tumors by staining." (PMID 31551495, 2019). "OR2B6 upregulation level was nearly 24-fold greater in invasive breast carcinoma patients (sub-population I) than in human breast cancer cell lines (group I)." (PMID 31551495, 2019). "In particular, the expression of Olfactory Receptor Family 2 Subfamily B Member 6 (OR2B6), which is a differentially expressed gene, was detected in most breast carcinoma tissues." (PMID 31036036, 2019). "Analyzing the OR gene upregulation among breast cancer cell lines showed that OR2B6 and OR2W3 were abundant similar to invasive breast tumors." (PMID 31551495, 2019). "Thereafter, we focused on the expression of OR2B6 in breast carcinoma cell lines and cell lines that originated from other types of carcinoma." (PMID 29497600, 2018). "Immunohistochemical staining of OR2B6 in breast carcinoma tissues revealed a distinct staining pattern of carcinoma cells." (PMID 29497600, 2018). "Immunohistochemical analyses confirmed the existence of OR2B6 at the protein level and revealed a distinct staining in native breast carcinoma tissues." (PMID 29497600, 2018). "The expression of OR2B6 was detectable in breast carcinoma tissues; here, transcripts of OR2B6 were detected in 73% of all breast carcinoma cell lines and in over 80% of all of the breast carcinoma tissues analyzed." (PMID 29497600, 2018). "We confirmed the expression of OR2B6 in breast carcinoma tissues, whereas it was hardly detectable in healthy breast tissues." (PMID 29497600, 2018). "In further studies, we will investigate the expression of OR2B6 in different breast cancer subtypes." (PMID 29497600, 2018). "To validate the NGS sequencing data of OR2B6 transcript expression, we confirmed the expression of OR2B6 in native breast carcinoma tissues via RT-PCR and observed the distribution of mapped reads using IGV." (PMID 29497600, 2018). "To improve the sensitivity of OR2B6 for breast carcinoma, we will correlate OR2B6 expression with clinical features like tumor grading, stage, and Heregulin2 status in upcoming studies." (PMID 29497600, 2018). "We did not observe different breast cancer subtypes, as the aim of our study is to demonstrate the overall expression of OR2B6 in breast cancer compared with healthy tissues." (PMID 29497600, 2018). "We analyzed the OR2B6 protein in native breast carcinoma tissue samples by performing immunohistochemical staining of breast carcinoma tissue samples using a specific antibody detecting OR2B6." (PMID 29497600, 2018).
breast carcinoma (continued). "Several studies have demonstrated their potential as therapeutic targets and prognostic biomarkers in cancer, with OR51E2, also known as the prostate-specific G-protein-coupled receptor, and OR2B6 showing overexpression in prostate and breast carcinomas, respectively." (PMID 39769144, 2024). "OR2W3 and OR2B6 were involved in breast cancer invasion and proliferation." (PMID 34065710, 2021). "Quantitative analysis of transcript abundance among the three sub-populations of OR genes confirmed that the genes associated with breast cancer cell proliferation (MKI67, AURKA, BIRC5, CCNB1, MYBL2) were significantly abundant in sub-population I with OR2B6 upregulation." (PMID 31551495, 2019). "Here, 43 of 45 breast carcinoma cell lines do express OR2B6 transcripts." (PMID 29497600, 2018). "Our analyses of breast carcinoma tissue samples and cell lines revealed that OR2B6 is nearly solely expressed in cancerous tissues and therefore might represent a tumor marker." (PMID 29497600, 2018). "Consistently, OR2B6 expression was detectable in breast carcinoma cells." (PMID 29497600, 2018). "We detected OR2B6 as a potential biomarker for breast carcinoma tissues." (PMID 29497600, 2018). "In summary, we identified a potential biomarker for breast carcinoma tissues, OR2B6." (PMID 29497600, 2018). "Further analyses need to elucidate whether OR2B6 has a functional role in breast carcinoma as well." (PMID 29497600, 2018). "In relation to breast cancer, OR2B6 and OR2W3 were ectopically expressed in breast cancer cell lines and breast cancer tissues making them potential biomarkers." (PMID 34367982, 2021). "Human breast cancer tissues and cell lines highly express ORs, among which only three, OR2W3, OR2B6, and OR2T6, have established functions." (PMID 34065710, 2021). "The few breast carcinoma samples, which did not elicit OR2B6 expression, require further investigation." (PMID 29497600, 2018). "We detected OR2B6 in human breast carcinoma cell lines and in breast carcinoma tissues, but not in healthy tissues." (PMID 29497600, 2018). "One receptor, OR2B6, had a pronounced expression in over 80% of all breast carcinoma tissues and 70% of all breast carcinoma cell lines, whereas it is not expressed in normal breast tissues." (PMID 29497600, 2018).
lung carcinoma (2 papers, 2018 to 2022). "In lung carcinoma tissues, OR2B6 was expressed in 30% of all samples, excluding OR2B6 as a reliable tumor marker for this carcinoma type." (PMID 29497600, 2018). "Likewise, it has been found that some ORs (in particular OR2B6) are over-expressed in some types of cancer, such as breast and lung cancer." (PMID 35620002, 2022).
aortic aneurysm (1 paper, 2024). A ruptured aneurysm located in the wall of the proximal portion of the descending aorta proceeding from the arch of the aorta. "In addition, evaluating the function of other, similar receptors found on the platelet surface (OR2W3, OR2B6) in the context of aortic aneurysm and vascular wall inflammation may provide additional context regarding platelet activation in these cases." (PMID 39768700, 2024).
embryonal carcinoma (1 paper, 2018). A non-seminomatous malignant germ cell tumor characterized by the presence of large germ cells with abundant cytoplasm resembling epithelial cells, geographic necrosis, high mitotic activity, and pseudoglandular and pseudopapillary structures formation. "OR2B6 is detectable in cell lines originated from other carcinoma types as well, such as colon and gastric carcinoma cell lines, with FPKM values of up to 0.86, in a pluripotent embryonal carcinoma cell line (FPKM value: 2.16) as well as in a melanoma cell line (FPKM value: 1.42)." (PMID 29497600, 2018).
endometriosis (1 paper, 2022). The growth of functional endometrial tissue in anatomic sites outside the uterine body. "Therefore, the combination of TRF396 and the gene OR2B6 may be a contributor to the pathogenesis of endometriosis, which provides a direction for future research." (PMID 35281615, 2022).
heart failure (1 paper, 2023). Inability of the heart to pump blood at an adequate rate to meet tissue metabolic requirements. "OR51E1 and OR2B6 were used as examples of ORs expressed in cardiomyocytes that were respectively down-regulated and upregulated with heart failure." (PMID 37762009, 2023).
invasive breast carcinoma (1 paper, 2019). A carcinoma that infiltrates the breast parenchyma. "Overall, our results suggest that specific sub-populations of invasive breast carcinoma patients have abundance of OR2B6, whereas others have abundance of OR2T8 or OR2W3." (PMID 31551495, 2019). "OR2B6, OR2T8 and OR2W3 were significantly upregulated in sup-populations of invasive breast carcinoma patients." (PMID 31551495, 2019). "However, upregulation of OR2B6 and OR2T8 did not have any significant effect on the survival probability of the invasive breast carcinoma patients." (PMID 31551495, 2019).
pancreas carcinoma (1 paper, 2018). "We could detect OR2B6 in the lung and in pancreas carcinoma tissues as well, whereas in the latter, OR2B6 shows the second highest expression." (PMID 29497600, 2018).
pancreatic carcinoma (1 paper, 2018). "The second highest expression was observed for OR2B6, which was expressed in 10 of 20 pancreatic carcinoma samples." (PMID 29497600, 2018).
cancer (5 papers, 2018 to 2024). A tumor composed of atypical neoplastic, often pleomorphic cells that invade other tissues. "While detecting OR2B6 transcripts in several cell lines that originated from different carcinoma tissues, we investigated the expression profile of OR2B6 in lung, pancreas, and brain carcinoma tissue samples." (PMID 29497600, 2018). "Furthermore, we investigated the expression of OR2B6 in other carcinoma tissues and corresponding healthy tissues." (PMID 29497600, 2018). "In the remaining carcinoma tissue samples and cell lines that originated from brain carcinomas, OR2B6 was not detectable." (PMID 29497600, 2018). "In addition, we showed that OR2B6 builds a fusion transcript with a histone gene, HIST1H2BO, in several carcinoma tissues." (PMID 29497600, 2018). "It is important to mention that OR2B6 unlike OR51E1 and OR51E2 lacks expression in healthy tissues, ensuring that the high expression does not come from an increase of a specific cell type but from the existence of the different transcript repertoire in cancer cells." (PMID 29497600, 2018).
OR2B6 also shares sentences with these, for which no sentence is quoted: COVID-19 (1 paper); gastric carcinoma (1); melanoma (1); prostate carcinoma (1); tumor (1).